MMP7 (matrix metallopeptidase 7)
Diseases named in the same sentence as MMP7 in open-access papers (continued):
Sharing a sentence is not in itself a finding about the gene and the disease.
infection (continued). "At the peak of infection, when animals developed the most severe lesions, infected animals had higher levels of several gene transcripts involved in cellular proliferation and inflammation, including matrix metalloproteinase-7 (MMP7), transglutaminase-2 (TGM2), and oncostatin M (OSM)." (PMID 30696739, 2019). "Therefore, it is possible that in the context of inflammation or infection, MMP-7 secreted from other cellular sources may reach the basolateral compartment of the epithelium and promote epithelial cell migration and proliferation." (PMID 20628524, 2010). "To determine the functional role of MMP-7 during IAV infection, we infected MMP-7 null mice (MMP-7KO) with IAV and examined glycocalyx shedding and lung injury on day 7 post-infection." (PMID 39312544, 2024). "Both MMP-7 and its inhibitor TIMP-1 were upregulated in IAV infected mice: MMP-7 colocalized with IAV, while TIMP-1 was limited to cells adjacent to infection." (PMID 39312544, 2024). "In response to injury or infection, the ectodomain of CD138 is proteolytically shed from the cell surface by matrix metalloproteinases (MMPs), such as MMP9 and matrilysin (MMP7)." (PMID 34364875, 2021). "Although molecular components of the gut epithelial barrier such as metalloproteinase-7 (MMP-7) and syndecan-2 are known to be associated with inflammation, little has been reported about MMP-7 expression and syndecan-2 shedding in response to ETBF infection." (PMID 34769248, 2021). "Endogenous mmp2, mmp7, mmp9, DKK-1, c-myc and CCND-1 mRNA and β-catenin protein expression levels were detected in P1-infected ST cells at 24, 48, and 72 h post-infection and compared with those in uninfected cells." (PMID 29593670, 2018). "Here, we assayed MMP2, MMP7, MMP9, TIMP1, and TIMP2, which have previously been described to be differentially expressed after infection of the CNS." (PMID 30442185, 2018). "In vitro, heparinase treatment before infection led to a 52% increase in viral load (p = 0.0038) without altering MMP-7 or TIMP-1 protein levels." (PMID 39312544, 2024). "A body of studies recorded increased MMP-7 and MMP-9 activity in blood circulation when patients were admitted to hospital after being infected with this disease, characterizing the initial phase of the infection." (PMID 37372128, 2023). "Specifically, KIM1 and MMP7 protein levels are significantly increased in acute MHV-1 infections, while a significant increase in EGFR protein level was identified long-term post-infection." (PMID 37626956, 2023). "In addition, expression of MMP-7 or MMP-3 in the liver or small intestine, respectively, increased upon infection, and this was suppressed by anti-TNF-α Ab treatment." (PMID 37939119, 2023). "Future exploration is needed to clarify whether ETBF infection affects MMP-7 expression and syndecan-2 release in vivo and whether the released syndecan-2 regulates the pro-MMP-7 activation process in BFT-exposed IECs." (PMID 34769248, 2021). "Vitamin D therapy of PBMCs decreases the MMP-10, MMP-1, and MMP-7 expression while increasing the TIMP-1 expression, indicating its critical function in preventing cellular injury and providing symptom relief while having an infection." (PMID 34944659, 2021). "Lentiviral infection with a dominant-negative JNK1 plasmid (lentivirus-dn-JNK) did not affect MMP-7 expression, either." (PMID 34769248, 2021). "The levels of cyclin D1, mmp7 and mmp9 mRNA in livers and spleens of the P1 infection group did not change significantly, but significantly decreased in kidneys and livers compared with those in the mock infected group." (PMID 29593670, 2018). "The levels of mmp7 and mmp9 mRNAs in the P1 infection group did not change significantly compared to those in the mock infected group in spleens, while significantly decreased in kidneys, hearts, and livers." (PMID 29593670, 2018).
infection (continued). "Although cells expressing MMP7 in chickens have not been identified, MMP7 was not induced in the spleen following intravenous infection and leukocyte subpopulations were also not responsible for its expression in the caecum (unpublished observations)." (PMID 25475706, 2014). "Except for MMP7, the gene expressions characterized in this study were not triggered after infection with the non-invasive SPI1 mutant of Salmonella Enteritidis." (PMID 23687968, 2013). "Thus, an imbalance between the circulating levels of specific MMPs and TIMPs—especially increased MMP-1 and MMP-8 to TIMP-4 and decreased MMP-1 and MMP-7 to TIMP-1 and 2—is characteristic of filarial lymphedema in the presence of active infection." (PMID 22679524, 2012). "There was no increase in the level of MMP-7 or MMP-9 after infection." (PMID 37939119, 2023). "When recruited to a site of infection, contact with microbial ligands will trigger HDP release and their subsequent activation by serine proteases in the case of cathelicidins and defensins depending on species and tissue amongst others by trypsin, kallikreins or matrix metalloproteinase-7 (MMP-7)." (PMID 30060758, 2018). "In addition, it could also reduce the expression of MMP-7, MMP-9, and MMP-10 in human peripheral blood monocytes, and increase the expression of TIMP-1, a tissue inhibitor of MMP, to eliminate tissue damage and relieve symptoms of infection." (PMID 38966394, 2024). "Ileal RNA expression of the alpha-defensin AMPs, Defa5, and Defa6, as well as MMP7, was significantly lower in Ptpn2∆IEC vs. Ptpn2fl/fl mice, after mAIECred but not K12 infection." (PMID 40955058, 2025). "The matrix metalloproteinase 7 (MMP-7) released from the PEDV-infected nasal epithelial cells (NECs) contributed to the destruction of endothelial integrity by degrading the tight junctions, rather than direct PEDV infection." (PMID 35435723, 2022).
kidney disease (13 papers, 2014 to 2024). "This study evaluated the role of urinary MMP-7 as a preliminary indicator of kidney disease in individuals with T2DM." (PMID 39246865, 2024). "Reviews about the regulation, role, and mechanisms of MMP-7 in the pathogenesis of kidney diseases have recently been provided." (PMID 37298105, 2023). "MMP-7 is involved in fibrotic development across tissues, and specifically in kidney disorders where it has been suggested to mediate tubulointerstitial fibrosis." (PMID 35136035, 2022). "They highlighted that the level of MMP-7 in the urine can be used as a potential non-invasive biomarker of kidney disease." (PMID 36359366, 2022). "The diverse actions of MMP-7 in kidney diseases are presumably mediated by its ability to cleave different substrates." (PMID 32630493, 2020). "In the past several years, significant progress has been made in our understanding of the biology of MMP-7 in kidney diseases." (PMID 32630493, 2020). "In this review, we summarized recent advances in our understanding of the regulation, role, and mechanisms of MMP-7 in the pathogenesis of kidney diseases." (PMID 32630493, 2020). "These novel actions of MMP-7 play a crucial role in mediating its diverse functions in the pathogenesis of kidney disorders." (PMID 32630493, 2020). "In this review, we discussed the expression, regulation, novel substrates, and mechanisms of MMP-7 in various kidney diseases." (PMID 32630493, 2020). "Consistent with animal studies, the induction of MMP-7 expression is also evident in the kidney from patients with various renal disorders." (PMID 32630493, 2020). "As our transcriptome data showed increased gene expression of MMP-7 and we recently identified MMP-7, released primarily by PTECs, as biomarker for kidney disease progression, we also used mass spectrometry to measure MMP-7 levels in the cell culture supernatant of PTECs." (PMID 39143064, 2024). "Interestingly, serum and urinary levels of MMP-7 can predict progression across multiple kidney disease states and reflect the renal fibrotic stage." (PMID 35136035, 2022). "The function of MMP-7 in kidney diseases is complex and context-dependent." (PMID 32630493, 2020). "Expression of matrix metalloproteinase-7 (MMP-7) in kidney diseases." (PMID 32630493, 2020). "Instead, the focus of this review is on MMP-7 in kidney diseases." (PMID 32630493, 2020). "In this context, it is conceivable that MMP-7 may be more important than other MMPs to the pathogenesis of kidney diseases." (PMID 32630493, 2020). "MMP7 may be more crucial factors than other MMPs in the pathogenesis of kidney diseases." (PMID 36359366, 2022). "Therefore, the role of MMP-7 as a therapeutic target for kidney disease needs further study." (PMID 34483931, 2021). "MMP-7 is upregulated in various kidney diseases, and its protein is predominantly distributed in the apical region of tubular epithelial cells and is detected in the fluids present in the tubular lumen, suggesting that this protein could be secreted to the urine." (PMID 32630493, 2020). "Furthermore, the role of MMP-7 may also evolve with different disease types or the time course of kidney disorders." (PMID 32630493, 2020). "Thanks to the availability of MMP-7 knockout mice, we now have a better understanding of the role of MMP-7 in the pathogenesis of kidney diseases." (PMID 32630493, 2020). "Numerous novel substrates of MMP-7 have been identified, enabling us to better comprehend the exact role of MMP-7 in the pathogenesis of kidney disorders." (PMID 32630493, 2020). "Because urine MMP-7 originates in the kidneys, it is more credible than serum MMP-7 in patients with kidney disease, regardless of their glycemic status." (PMID 39246865, 2024). "Given this, we planned this study to evaluate urine MMP-7 levels in individuals with or without renal disease and T2DM." (PMID 39246865, 2024).
kidney disease (continued). "Under normal physiologic conditions, MMP-7 is almost not expressed in adult kidneys but upregulated in various renal diseases, including AKI and CKD." (PMID 34483931, 2021). "The WNT pathway activity, induced by TGF‐β signaling, is also increased in DKD and urinary excretion of MMP‐7 (matrix metalloproteinase 7), a target gene highly upregulated by WNT pathway activation, is shown to correlate with renal WNT pathway activity in animal models of kidney disease." (PMID 24793984, 2014). "We compared the renal parameters like serum urea, creatinine, sodium, potassium, urine albumin, creatinine, urine ACR, eGFR, and urine MMP-7 levels among the participants with or without T2DM and kidney disease." (PMID 39246865, 2024).
inflammation (11 papers, 2007 to 2025). Aberrant reaction of the microcirculation characterized by movement of fluid and leukocytes from the blood into extravascular tissues. "Here, the upregulations of MMP-7 were detected during lung inflammation in vivo and in vitro." (PMID 34630854, 2021). "The qPCR results indicated that both PACEL and three indole analogues could alleviate DSS-induced intestinal inflammation in mice by inhibiting pro-inflammatory cytokines (MMP7, IL1α) and down-regulating BMP8B expression, thus preventing carcinogenesis of normal colonic epithelial cells." (PMID 37927593, 2023). "Lungs from septic animals and from septic humans demonstrated acute lung inflammation, collagen deposition, and marked increase of WNT5A and MMP7 protein levels." (PMID 25331176, 2014). "Mice without MMP7 are protected from lethal doses of lipopolysaccharide (LPS)-induced systemic inflammation, showing reduced intestinal permeability and lung inflammation." (PMID 40341670, 2025).
adenocarcinoma (10 papers, 2008 to 2023). A common cancer characterized by the presence of malignant glandular cells. "There was a clear co-upregulation of PEA3 and ER81 with MMP-1 and, to a lesser extent, MMP-7 in adenocarcinoma samples, suggesting a causative role for PEA3 subfamily members in driving MMP-1 expression." (PMID 21143918, 2010). "We found that shed SDC-1 and MMP-7 levels were significantly lower, whereas Mesothelin and Galectin-1 levels were significantly higher in malignant mesothelioma effusions, compared to adenocarcinoma." (PMID 32731396, 2020). "In order to identify a potential clinical relevance for MMP7 in human coloncarcinoma we screened publicity available human adenocarcinoma datasets for different hystopathological and prognostic parameters." (PMID 25596746, 2015). "We found that the expression pattern of PLA2G3 was more similar to that of MMP-7, which was also increased in both left and right colon adenocarcinomas." (PMID 18212756, 2008). "A previous study showed that MMP7 was not required for malignant cell invasion in Smad4-deficient adenocarcinomas." (PMID 25424420, 2014). "Thus MMP7 is not needed for tissue invasion in Smad4-deficient adenocarcinomas." (PMID 25424420, 2014). "Single nucleotide polymorphisms (SNPs) at four TIMP (TIMP1-4) and three MMP genes (MMP2, MMP7 and MMP9) were genotyped in DNA samples from a prospective cohort of patients with primary adenocarcinoma of the GEJ admitted to the British Columbia Cancer Agency." (PMID 23527119, 2013).
prostate (10 papers, 2011 to 2022). "The aging of the kidney modulates the expression of various genes, e.g., the levels of mRNA of claudin-7, KIM-1, and metalloproteinase MMP-7, which are good markers associated with renal injury and various kidney pathologies." (PMID 30360430, 2018). "rLRR20 colocalized with E-cadherin on the cell surface and activated the downstream transcription factor β-catenin, which subsequently promoted the expression of MMP7, a kidney injury biomarker." (PMID 34884937, 2021). "MMP7 can promote pulmonary neutrophil recruitment and chemokine dependent angiogenesis, two important processes in the development of lung fibroplasia." (PMID 32171287, 2020).
cardiovascular disease (9 papers, 2017 to 2025). "At the genetic level, functional polymorphisms in the MMP7 gene have been linked to cardiovascular disease susceptibility and outcomes." (PMID 39200884, 2024). "Taken together, these studies provide compelling evidence for the involvement of MMP-10 and MMP-7 in cardiovascular disease pathogenesis in multiple arterial beds." (PMID 40563493, 2025). "The role of MMP‐7 in cardiovascular disease is controversial: although in animal models MMP‐7 gene knockout reduces atherosclerotic burden, mice with the knockout have a greater risk of sudden death and cardiac fibrosis." (PMID 37939716, 2024). "Several studies have been reported that MMP-7 and MMP-8 increased the risk of incident cardiovascular disease events." (PMID 31752174, 2019). "Among these proteins, matrix metalloproteinases such as MMP-7 and MMP-10 have emerged as key regulators in the development of cardiovascular diseases." (PMID 40563493, 2025). "In this study (in a subgroup of non-diabetics, n = 515) it was shown that serum levels of MMP-7 and -12 were significantly elevated in subjects with signs of cardiovascular disease (n = 270) whereas levels of MMP-1,-3 and-10 were unaffected." (PMID 30789935, 2019).
colon (5 papers, 2008 to 2024). "As a second example, MMP7 is enriched in CRC and exhibited medium abundance in other digestive system neoplasms." (PMID 39393173, 2024). "It is widely reported that cytokines (IL1β, TNF-α), matrix metalloproteinase (MMP-7, MMP-9) are involved in chronic inflammation, which creates a microenvironment favoring colon carcinogenesis." (PMID 23754197, 2013).
colon polyp (5 papers, 2015 to 2023). "Indeed, silencing MMP-7 in mice will result in the inability to activate pro-α-defensins in the gut and a higher susceptibility to intestinal bacterial infections." (PMID 28738067, 2017). "In our study, we found that β-catenin levels increased concurrently with its pro-proliferative targets MYC and MMP-7 in the Hnf1A98V polyps, while CDX2 levels were depressed in the colonic polyps but not in the adjacent tissue." (PMID 37219942, 2023).
bacterial infection (3 papers, 2016 to 2025). "Therefore, while MMP7 may be involved in bacterial translocation at the level of the intestines and LPS-induced inflammation, these effects seem to be redundant in the context of a live bacterial infection treated with antibiotics." (PMID 40341670, 2025).
connective tissue disease (3 papers, 2018 to 2025). "IPA demonstrated the involvement of relevant genes (OPN, POSTN, MMP-1, MMP-7, Prominin-1, and others) in the network “connective tissue disease, organismal injury and abnormality”, and other functions related to cell movement and connective tissue disorder." (PMID 30111332, 2018). "Concerning early connective tissue disease (CTD)-ILD+ diagnosis, increased MMP-7, MMP-9, MMP-10, and MMP-12 levels were found in RA-ILD+ and SSc-ILD+ patients in relation to RA-ILD- and SSc-ILD- patients, respectively." (PMID 39979794, 2025).
hematological disease (2 papers, 2013 to 2024). "We found that high expression of SEC61A1 was associated with upregulation of EPHA3, MMP7, BIRC7, and ROS1, all of which have been reported as prognostic markers or therapeutic targets in hematological malignancies." (PMID 38584833, 2024).
MMP7 also shares sentences with these, for which no sentence is quoted: benign tumors (3 papers); glioblastoma (3); metastasis (3); ovarian endometriosis (3); renal carcinoma (3); renal failure (3); ulcerative colitis (3); amyloidosis (2); bipolar disorder (2); brain glioma (2); chorioamnionitis (2); cystitis (2); endometrial tumors (2); esophagogastric junction adenocarcinoma (2); Familial adenomatous polyposis (2); Hepatic steatosis (2); intraductal papillary mucinous neoplasms (2); multiple myeloma (2); Myocardial fibrosis (2); non-alcoholic fatty liver disease (2); triple-negative breast carcinoma (2); acute lymphoblastic leukemia (1); acute respiratory failure (1); AIDS (1); airway hyperresponsiveness (1); Alagille syndrome (1); alcoholic hepatitis (1); apical periodontitis (1); Arrhythmia (1); asbestosis (1).
A further 99 diseases each share a sentence with MMP7 in 1 paper.